CCND1 (cyclin D1)
Diseases named in the same sentence as CCND1 in open-access papers (continued):
Sharing a sentence is not in itself a finding about the gene and the disease.
ovarian carcinoma (continued). "In addition, PSMC2 may regulate ovarian cancer through CCND1, knockdown of both in combination could induce intense inhibition effects on the development and progression of ovarian cancer." (PMID 34294689, 2021). "In this study, RPS6 knockdown resulted in decreased Cyclin E, CDK2, Cyclin D1, CDK4, and CDK6 levels, and reduced Rb phosphorylation, thus hindering the transition from G0G1 to S phase, causing most cells to be blocked in G0G1 phase, thereby inhibiting ovarian cancer cell growth." (PMID 32862831, 2020). "To address whether PITX2 regulates these genes in promoting cell growth of ovarian cancer cells, we firstly performed Q-PCR analysis and showed that there was 2–12 folds increase in expressions of Cyclin-D1 and C-myc in PITX2 stably expressing ovarian cancer cells." (PMID 22615897, 2012). "Genistein has indicated upregulation of cyclin D1 and CDK4 expression, thereby promoting the proliferation and viability of ovarian cancer OVCAR‐5 cells." (PMID 40634118, 2025). "Our results show that Wnt3A upregulates canonical β-catenin targets in ovarian cancer cells with functional BRCA1 and BRCA2, particularly the full-length WT Tcf1/7, c-Myc, and cyclin D1." (PMID 39028933, 2024). "By screening 31 drugs with 110 targets, FNTA, HSPA5, NEU1, CCND1, CASP1, CASP3 were negatively correlated with ovarian cancer, and HMGCR, PLA2G4A, ITGAL, PTGS1, FNTB were positively correlated with ovarian cancer." (PMID 38651149, 2024). "Our data proved that HMGB3 activates MAPK/ERK signaling in ovarian cancer, as indicated by increased MEK1/2 and ERK1/2 phosphorylation, and the upregulation of its downstream molecules, including ETS-1, CCND1, and c-Myc." (PMID 37328851, 2023). "CircATRNL1 absorbs miR-378, activates Smad4, and further decreases the activities of Akt, Cyclin D1, MMP2 and MMP9, thereby inhibiting proliferation, angiogenesis and metastasis of ovarian cancer cells." (PMID 37940982, 2023). "We treated ovarian cancer cell lines with OSU-ERb-12 and determined the ERα protein level and expression of two ERα target genes, CCND1 and NRIP1." (PMID 35565440, 2022). "The expression levels of CCND1 gene in normal ovarian epithelial cells and SKOV3 ovarian cancer cells were detected by RT-PCR." (PMID 34806539, 2021). "HOTAIR modulates CCND1 and CCND2 expression through regulating miR-206 expression in ovarian cancer." (PMID 34592939, 2021). "CCND1, also known as cyclin D1, was identified as a potential downstream of PSMC2, which regulate the development of ovarian cancer in together with PSMC2." (PMID 34294689, 2021). "The levels of p-RB, cyclin D1, cyclin E, CDK2, CDK4, or CDK6 by RPS6-KD were reduced in NSCLC cells, ovarian cancer cells, and drug-resistant melanoma cells." (PMID 35008473, 2021). "shBTG2 caused a notable increase in the expression of the cell cycle proteins Cyclin D1 and CDK4, while GV-BTG2 decreased Cyclin D1, CDK4 and CDK2 expression in ovarian cancer cells." (PMID 34485119, 2021). "Inhibiting downstream targets such as Survivin, C-Myc, Cyclin D1, and others by LLL12B, is likely one of the main mechanisms of sensitizing ovarian cancer cells to cisplatin or paclitaxel and likely one the main mechanisms of synergism by drug combination." (PMID 33909625, 2021). "Consistently, the G0/G1 checkpoint regulators, such as cyclin D1, cyclin E, CDK2, CDK4, CDK6, and p-RB, are diminished by RPS6-KD in ovarian cancer cells." (PMID 35008473, 2021). "The results of the western blot assay indicated that trichodermin significantly suppressed the expression of cyclin D1, CDK4, CDK2, p-Rb, and Rb in both ovarian cancer cell lines." (PMID 34065149, 2021).
ovarian carcinoma (continued). "The two cancer promoters, respectively CCND1 and CCND2, were overexpressed in the ovarian cancer samples, their expression is directly correlated with the upregulated level of HOTAIR." (PMID 34207450, 2021). "In our study, MIR502 was down-regulated in ovarian cancer, and the expression of CCND1 was negatively correlated with MIR502, which means CCND1 is overexpressed in OC." (PMID 32660514, 2020). "Among which, elevation in the gain-of-function R248Q mutant p5326, cyclin D1 and β catenin, known to transcriptionally regulate cyclin D127, as well as vimentin which like β catenin is involved in EMT and ovarian cancer progression." (PMID 32728020, 2020). "The PPI network further demonstrated that CCND1 and MYCN were at core positions in the development of ovarian cancer." (PMID 32660514, 2020). "Treating cisplatin-resistant ovarian cancer cells with HO-4200 and H-4318 decreases the level of STAT3 target proteins: c-myc, Bcl-2, Bcl-xl, survivin and cyclin D1/D2, giving rise to inhibition of cell survival and induction of apoptosis." (PMID 31949487, 2020). "In ovarian cancer cells, MSX1 performs inhibition of cyclin D1 (CCND1) in addition to other cyclins and cell cycle regulators, while, in primary mesenchymal and epithelial progenitor cell types, MSX1 activates CCND1." (PMID 31779217, 2019). "In conclusion, our study identifies a novel molecular mechanism for E2F1, whereby it targets miR-519d to upregulate RhoC, Bcl-2, cyclin D1, survivin, MMP2, MMP9, STAT3 and HuR expression, promoting tumorigenesis and progression in ovarian carcinoma." (PMID 28146423, 2017). "To validate the GSEA results, we then detected the levels of Cyclin D1, CDK4, p16, AKT, p-AKT, mTOR, p-mTOR, p70S6K1 and p-p70S6K1 in ovarian cancer cells with AE2 silenced." (PMID 28743911, 2017). "MiR‐490‐3p plays a tumour suppressor role in epithelial ovarian cancer by targeting CDK1 regulation and influencing SMARCD1 and cyclin D1 (CCND1) expressions." (PMID 28598010, 2017). "Altogether, our findings show that overexpression of miR-634 leads to direct repression of RSK2, CCND1, GRB2 and ERK2 in ovarian cancer cell lines and ovarian cancer cells derived from patients." (PMID 26576679, 2015). "In this study, EVO exerted its activity by downregulating the cyclin D1 protein expression and inducing apoptosis in a xenograft mouse model, in which CPT-resistant ovarian cancer cells were transplanted." (PMID 26207989, 2015). "The results demonstrated that following transfection of the WWOX gene, ovarian cancer stem cells expressed significantly lower levels of cyclin E, CDK2, cyclin D1 and CDK4 proteins than the empty plasmid group and the control group." (PMID 25891642, 2015). "Previous reports showed that poor prognosis of ovarian cancer patients correlates with overexpression of pro-MMP-9 and cyclin D1, whose expression is known to be regulated by NF-κB." (PMID 24533079, 2014). "A more detailed understanding of the β-catenin and cyclin-D1 role in Wnt signaling pathway may be helpful in the investigation of the molecular mechanisms presented in hUCMSCs-LV-IL-21, and may improve therapeutic strategies involving hUCMSCs-LV-IL-21-mediated targeting therapy of ovarian cancer." (PMID 24444073, 2014). "The cyclin D1/CDK4 complex is responsible for cell cycle progression in early G1 phase and is frequently overexpressed in various human carcinomas including ovarian cancer." (PMID 25180593, 2014). "miR-193a induced the inhibition of DNA synthesis and apoptosis by targeting genes including ARHGAP19, CCND1, ERBB4, KRAS, MCL1, indicating a tumor suppressive role of this miRNA in epithelial ovarian cancer cells." (PMID 23588298, 2013).
ovarian carcinoma (continued). "In addition, it was previously reported that COX-1, COX-2 and cyclin D1 were all up-regulated in ovarian cancer, and downregulation of cyclin D1 expression via a COX-2 dependent mechanism by celecoxib could be a potential mechanism to inhibit ovarian cancer growth." (PMID 22949827, 2012). "We next evaluated the potential of 25HC to regulate the expression of well known ERα target genes, such as pS2, PR, Cathepsin D, Cyclin A and Cyclin D1 in MCF7 breast and BG-1 ovarian cancer cells." (PMID 21304949, 2011). "Knocking down PYGB also significantly inhibited the expressions of Wnt3a, β-catenin, APC, and Cyclin D1 in ovarian cancer cells, suggesting that, through the Wnt/β catenin signaling pathway, PYGB might regulate the progression of ovarian cancer." (PMID 38334681, 2024). "Additionally, miR-206 targets CCND1 and CCND2, inhibiting the proliferation, progression, migration, and invasion of ovarian cancer cells." (PMID 38793064, 2024). "Second, we established that icodextrin appeared not to promote ovarian cancer cell proliferation by assessment of the expression of cyclin D1 and B1 proteins, the two crucial cell proliferation markers." (PMID 35334562, 2022). "The expression level of CCND1 gene significantly affected OS and PFS of ovarian cancer patients." (PMID 34806539, 2021). "Moreover, gene microarray was used to analyze the alteration of gene expression profiling of ovarian cancer induced by PSMC2 knockdown and identify CCND1 as a potential downstream of PSMC2." (PMID 34294689, 2021). "Another recent study performed in ovarian cancer cell lines showed the overexpression of PKM2 that in turn increased CCND1 expression, whereas it decreased CDKN1A expression; determinants involved in the increase of proliferation and in the decrease of apoptosis of ovarian cancer cells." (PMID 32326107, 2020). "HOTAIR regulates CCND1 and CCND2 expression by sponging miR-206 in ovarian cancer." (PMID 32349783, 2020). "The results showed that the expression rates of eIF4E and cyclin D1 proteins in ovarian cancer tissues were significantly higher than those in noncancerous epithelial ovarian tissues (P = 0.001 and P = 0.032, respectively)." (PMID 33489719, 2020). "The following researches confirmed that HOTAIR negatively regulated miR-206 to activate STS2 33 to promote cancer invasion of head and neck squamous cell carcinoma as well as to activate CCND1 and CCND2 34 to stimulate the proliferation, and invasion of ovarian cancer cells." (PMID 32489462, 2020). "The expression rate of eIF4E and cyclin D1 in ovarian cancer tissues was significantly higher than that in noncancerous epithelial ovarian tissues (P = 0.001 and P = 0.032, respectively)." (PMID 33489719, 2020). "A subset of ovarian cancer is known to overexpress CCNE1 or CCND1, suggesting that cell-cycle-targeted drugs such as palbociclib, a CDK4/6 inhibitor, may be effective in specific subsets of ovarian cancer." (PMID 31052165, 2019). "In summary, we believe that DLEU1 promotes the pathogenesis and development of epithelial ovarian cancer through its interaction with miR‐490‐3p, thereby altering the expression of the miR‐490‐3p target genes, that is, CDK1, CCND1 and SMARCD1, as well as the expression of MMP2, Bcl‐xLand P70S6K." (PMID 28598010, 2017). "The following genes were overexpressed in various tumors: CCND1 in colorectal and renal cancers, and sarcoma; CCNE1 in colorectal, lung, stomach, esophagus, head and neck, uterine and ovarian cancers, and sarcoma; and CDKN2A in lung, uterine, and ovarian cancers." (PMID 28258440, 2017).
ovarian carcinoma (continued). "Our data showed that induction of apoptosis and cell cycle G1 arrest are key components of the anti-tumorigenic effects of NT1014 in ovarian cancer cells, as evidenced by induced expression of annexin V, p27, and p21 as well as reduction of BCL, Mcl-1, cyclin D1, and CDK expression." (PMID 27655410, 2016). "We show that miR-634 regulates cyclin D1 and several Ras-MAPK pathway components (GRB2, ERK2, RSK1 and RSK2), which may contribute to the effects of miR-634 on ovarian cancer cell survival and chemotherapy response." (PMID 26576679, 2015). "Our results demonstrated that the expression levels of SOX7 and its targets, COX-2 and cyclin D1, have an inverse relationship, further supporting our hypothesis that SOX7 is a negative regulator in the Wnt/β-catenin signaling pathway in ovarian cancer." (PMID 25297608, 2014). "In human ovarian cancer, deregulation of CCND1 expression mainly occurs without any gene amplification." (PMID 23236518, 2012). "Additionally, Western blot analysis also revealed that both Cyclin-D1 and C-myc elevated at least 60% in PITX2 stably expressing ovarian cancer cells." (PMID 22615897, 2012). "Likewise, in A2780 ovarian cancer cells, CGZ decreases cyclin D1 along with other pro-survival factors resulting in cell cycle arrest." (PMID 21283708, 2011). "In this study, to discuss the relationship between COX-2 and cyclin D1, we investigated the potential effect of Celecoxib on the growth of malignant ovarian tumors in a SKOV-3 cells mouse xenograft model and aimed to elucidate the molecular mechanism of its antitumor effect in relation to cyclin D1." (PMID 21152316, 2010). "Inhibition of PCDGF by antisense PCDGF transfection could downregulate the expression of cyclin D1, CDK4 and MMP-2, and markedly reverses malignant phenotype of ovarian cancer." (PMID 17261172, 2007). "CCND1 protein has been reported to be downregulated by hypoxia in at least two cell lines: the pheochromocytoma derived PC12 cell line and the ovarian carcinoma SKA cell line." (PMID 15026807, 2004). "We conclude that deregulation of CCND1 expression leading to both cytoplasmic and nuclear protein localization is a frequent event in ovarian cancer and occurs mainly in the absence of gene amplification." (PMID 10584879, 1999). "Nonetheless, it can also be considered that the presence of these truncated Tcf1/7 proteins may be the mechanism preventing the transcription of full-length Tcf1/7, Myc, and cyclin D1 and the preferential transcription of Axin2 instead in the BRCA2-null ovarian cancer cells." (PMID 39028933, 2024). "Among them, FNTA, HSPA5, NEU1, CCND1, CASP1, CASP3 had a negative causal association with ovarian cancer development, and HMGCR, PLA2G4A, ITGAL, PTGS1, FNTB had a positive causal association with ovarian cancer development." (PMID 38651149, 2024). "In addition aspirin may inhibit several targets such as HSPA5, NEU1, CCND1, CASP1, CASP3, which are negatively correlated with ovarian cancer prognosis." (PMID 38651149, 2024). "Moreover, the protein levels of cyclin D1 and B1 were not overexpression-elevated in icodextrin-treated ovarian cancer cells, either with an increasing concentration or with an increasing treated time." (PMID 35334562, 2022). "Moreover, the positive expression of eIF4E and cyclin D1 proteins was not related to the age of ovarian cancer patients (P > 0.05, respectively)." (PMID 33489719, 2020). "In this study, Western blot analysis demonstrated a dose-dependent reduction of cyclin D1 in human ovarian cancer cell lines, but not in non-cancerous IOSE cell cultures or in cervical tissues from individual animals treated for 6 weeks with the diet containing various SHetA2 doses." (PMID 29273857, 2018).
ovarian carcinoma (continued). "To summarize, we suggest that leptin may promote progression from G1 to S phase by stimulating expression of cyclin D1 and inhibiting that of p21WAF1/CIP1, as well as progression to the S phase by stimulating the expression of cyclin A in an ovarian cancer cell line." (PMID 22968658, 2013). "A decrease in important elements in this pathway, like P-PI3K, P-AKT, CCND1, CDK4, and P-RB, supports the idea that Kirenol could potentially inhibit this signaling cascade, providing new understanding of how it works and strengthening its potential as a hopeful treatment for ovarian cancer." (PMID 38415456, 2025). "Conversely, knockdown of PITX2 remarkably reduced the expressions of Cyclin-D1 and C-myc at least 20% compared to their scrambled controls in OVCA 433 and OV2008 cells.These findings indicate that PITX2 could upregulate Cyclin-D1 and C-myc in promoting cell growth of ovarian cancer cells." (PMID 22615897, 2012). "Therefore, in the present study, the lack of significant overexpression of the cyclin D1 or B1 proteins in the icodextrin-treated ovarian cancer cell lines, in either a dose- or time-dependent manner, further strongly suggests that icodextrin does not promote ovarian cancer cell proliferation." (PMID 35334562, 2022). "Given that we did not observe upregulation of Tcf1/7, Myc, and cyclin D1 in BRCA2-null ovarian cancer cells, the potential absence of these prosurvival mechanisms may very well contribute to the improved survival observed in patients with BRCA2 ovarian cancer." (PMID 39028933, 2024).